AKT2 (AKT serine/threonine kinase 2)
Diseases named in the same sentence as AKT2 in open-access papers (continued):
Sharing a sentence is not in itself a finding about the gene and the disease.
breast cancer (continued). "In addition to AKT3, AKT2 has also been found to have tumour suppressive functions in certain tissues as shown in two separate mouse models of breast cancer, where AKT2 deletion accelerated tumour development while AKT1 deletion inhibited tumour growth." (PMID 32453400, 2020). "Furthermore, the post-invasion survival of AKT2 overexpressing breast cancer cells is augmented and contributes to the increased metastatic potency in vivo." (PMID 31752925, 2019). "Even though AKT2 is not frequently over-amplified in breast cancer, its expression is linked with poor prognosis." (PMID 31357505, 2019). "AKT2 promoted breast cancer cell growth after stimulation of GPCR e.g. by SDF1α in this study." (PMID 31752925, 2019). "Mutations of AKT2 and AKT3 are rare events in breast cancer with a frequency of 0.4% each." (PMID 31752925, 2019). "In addition to the AKT pathway, Twist1 also positively regulates AKT2 expression by binding to E-box elements on the AKT2 promoter in breast cancer cells." (PMID 28099910, 2017). "Contrarily, knockout of AKT2 or its downstream molecules could be a better option to improve breast cancer treatment outcomes, at least for metastatic disease." (PMID 28287129, 2017). "Expression of both PIPP and AKT1 was reduced in a subset of human breast cancers and it is interesting to speculate that hyperactivated AKT2 in these tumours may promote metastasis leading to a poorer outcome although this has yet to be shown." (PMID 28082369, 2017). "Altogether, our results confirm that AKT2 has a promigratory role in breast cancer cells." (PMID 28287129, 2017). "Consequently, our study proposes that AKT2 constitutes a prognostic marker of poor clinical outcomes in breast cancer." (PMID 28287129, 2017). "Overexpression of AKT2 was frequently discovered in breast cancer and HCC22,23." (PMID 29051585, 2017). "Our study suggests that specific disruption of AKT2 may be preferable to panAKT inhibition for the treatment of advanced breast cancer." (PMID 28287129, 2017). "Our results show that AKT1 and AKT2 isoforms regulate breast cancer cells differently." (PMID 28287129, 2017). "In conclusion, AKT1 and AKT2 level might be used as biomarkers of breast cancer progression early in the diagnosis process to discriminate which subset of patients could progress sooner and consequently have potentially worse clinical outcomes." (PMID 28287129, 2017). "However, other findings challenge the dispensability of AKT2 in the progression of PTEN-deficient solid tumours including prostate and breast cancer and glioblastoma." (PMID 28082369, 2017). "Our findings suggest that miR-564 is a potential tumor suppressor that regulates both PI3K and MAPK signaling by directly targeting a network of genes (AKT2, GNA12, GYS1 and SRF) linked to these pathways, and thus controls breast cancer cells proliferation, EMT, migration and invasion." (PMID 27600857, 2016). "Three Akt isoforms are expressed in breast cancer cells (e.g. Akt1, Akt2,and Akt3)." (PMID 23874830, 2013). "In this manuscript, the impact of disrupting Akt1 or Akt2 in mammary tumors induced by IGF-IR overexpression were examined to determine whether specific Akt isoforms regulate different aspects of mammary tumorigenesis." (PMID 23919516, 2013). "An early study showed that Akt2 overexpression transformed mouse fibroblast NIH/3T3 cells, whereas another report indicated that Akt2 overexpression increased substantially metastatic features and invasion both in human breast cancer and human ovarian cell lines." (PMID 24381788, 2013). "AKT2 mediates tumor cell migration and invasion of breast cancer cells." (PMID 23468863, 2013).
breast cancer (continued). "In addition, Akt2 induces epithelial to mesenchymal transition, a process involved in de novo formation of breast cancer SCs59." (PMID 32309540, 2013). "This is further exemplified in breast cancer mouse models: while overexpression of AKT1 accelerates ErbB-2 mediated mammary tumorigenesis and suppresses tumor invasion, overexpression of AKT2 markedly increases the incidence of pulmonary metastases in breast cancer." (PMID 22666248, 2012). "Furthermore, recent evidence showed that Twist upregulates AKT2 expression in breast cancer cells leading to tumor development and progression." (PMID 22511931, 2012). "Akt2 and Akt3, are genomically amplified in several ovarian, pancreatic and breast cancers." (PMID 22511990, 2012). "Thus, AKT2 in these breast cancer cells was important in cell cycle progression and protective against autophagy through mitochondrial homeostasis." (PMID 22680924, 2012). "Thus, the data presented in this paper provide grounds that Akt2 can be one of the most promising targets for anti-cancer therapies, at least for breast cancer." (PMID 21297943, 2011). "We have analysed an additional 547 primary breast cancers without detecting AKT2 or AKT3 E17K mutations." (PMID 18813315, 2008). "Using a two-site chemiluminescence-linked immunosorbent assay, we measured the quantitative expression levels of total phosphorylated (P-S473) Akt (Akt1/Akt2/Akt3) on cytosol fractions obtained from fresh frozen tissue samples of 156 primary breast cancer patients." (PMID 15987444, 2005). "Several studies have found Akt2 to be amplified or overexpressed at the mRNA level in various tumour cell lines and in a number of human malignancies, such as colon, pancreatic and breast cancers." (PMID 15987444, 2005). "In this study, we sought to compare the concordance of pathogenic alterations in PIK3CA, AKT1, AKT2, AKT3, and PTEN detected by tissue-based FoundationOne®CDx and blood-based FoundationOne®Liquid CDx in contemporaneous samples collected from patients with breast cancer." (PMID 40597213, 2025). "In breast cancer, AKT2 may increase metastatic potential via several mechanisms." (PMID 33498407, 2021). "In contrast to the distinct functions of AKT1 and AKT2 in breast cancer, both isoforms exhibit a decreasing effect on migration, invasion and focal adhesion by inhibiting the activity of β1-integrin in prostate cancer cells which are also highly hormone-dependent like breast cancer cells." (PMID 31752925, 2019). "Therefore, inhibition of AKT2 could potentially be a good candidate for breast cancer treatment and should be further analyzed to probe its therapeutic use." (PMID 31357505, 2019). "Moreover, AKT2 is the critical isoform mediating metastasis of breast cancer." (PMID 31752925, 2019). "Additionally, high AKT2 kinase activity is displayed in 40% of breast cancer probes and is associated with late stage tumors, confirming a crucial role of AKT2 in tumor progression rather than in tumor initiation." (PMID 31752925, 2019). "Consequently, lung metastasis is also elevated in breast cancer cells overexpressing AKT2." (PMID 31752925, 2019). "Moreover, Pipp-deficient mammary cancer cells exhibited reduced cell migration and invasion in vitro, a defect rescued by the shRNA-mediated knockdown of Akt1 but not Akt2." (PMID 28082369, 2017). "Similarly, regulation of a number of AKT isoform-specific downstream effectors have been identified, including the degradation of nuclear factor of activated T cells (NFAT) mediated by AKT1 and up-regulation of β1-integrin by AKT2 that regulates breast cancer cell migration." (PMID 28082369, 2017). "Similarly, amplification or overexpression of AKT2 has been identified in HER2/neu positive (Her2/neu+) breast cancers as well as ovarian, prostate and pancreatic cancers correlating with poor prognosis, and increased risk of relapse and metastatic tumor formation." (PMID 27323778, 2016).
breast cancer (continued). "Recently, using insertion mutagenesis in an estrogen-dependent breast carcinoma cell line, a panel of 7 candidate breast cancer anti-estrogen resistant (BCAR) genes were identified that directly underlie estrogen independence leading to tamoxifen resistance, including both EGFR, AKT1, and AKT2." (PMID 24758408, 2014). "This may be due to different biological effects of Akt1 and Akt2 in HER2-positive breast cancer." (PMID 22842582, 2012). "The expression of several isoforms, such as AKT2 and TSC1, changes significantly across time, implicating these genes and their isoforms in breast cancer development and recurrence." (PMID 39888956, 2025). "Our study is one of the largest analytical studies of pathogenic alterations in PI3K/AKT pathway genes (PIK3CA, AKT1, AKT2, AKT3, and PTEN) among patients with breast cancer." (PMID 40597213, 2025). "PI3K/Akt/mTOR is a major pathway that participates in the regulation of cell survival and proliferation, and the essential genes of the PI3K/Akt pathway, PIK3CA, AKT1, AKT2, and PTEN, are often altered in breast cancer." (PMID 33435254, 2021). "To explore the therapeutic effect of the two out of three Akt isoforms (Akt1 and Akt2) in breast cancer and breast cancer metastasis, we employed mouse models that recapitulate HER2-enriched breast cancer and luminal B breast cancer." (PMID 35578699, 2021). "Amplification of AKT1, AKT2 and AKT3 has been reported in gastric, ovarian, pancreatic and breast cancers, glioma and melanoma." (PMID 34419139, 2021). "The AKT family consists of the three isoforms AKT1, AKT2, and AKT3, which are shown to be partly inversely correlated in the regulation of breast cancer growth and metastasis." (PMID 33670586, 2021). "A cBioPortal analysis shows ≈50% of breast cancers with genomic aberrations in PIK3CA, AKT1, AKT2, AKT3, and/or ESR1,suggesting relevance of this signaling axis in breast cancer." (PMID 33498407, 2021). "Metformin inhibited cell migration and invasion of several breast cancer cells and metastasis of MDA-MB-231 xenografts by upregulating miR-200c which negatively regulated Akt2 expression." (PMID 34298660, 2021). "For instance, miR‐520c‐3p inhibits the invasion and migration of breast cancer by targeting IL‐8 and suppresses the invasion and migration of lung cancer by targeting AKT1 and AKT2." (PMID 33340250, 2021). "Systemic Akt1 deletion inhibited lung metastases whereas systemic Akt2 deletion enhanced mammary tumorigenesis and metastasis at least in HER2-enriched and luminal B mouse models of breast cancer." (PMID 34298660, 2021). "It has been reported that the ratio of AKT1 and AKT2 expression regulates EMT and CSC properties in a breast cancer model." (PMID 31600013, 2020). "A recent study showed that AKT2 inhibition has the potential for anticancer therapies for its function in EMT reversion, metastasis reduction, and tumor recurrence prevention in breast cancer." (PMID 33123457, 2020). "The ratio of AKT1 and AKT2 has been reported to regulate EMT and CSC traits through regulation of miR‐200s in breast cancer." (PMID 31600013, 2020). "Because AKT1 and AKT2 have been shown to differentially regulate invasion and proliferation in breast cancer 35,36, we used isoform-specific antibodies to measure AKT1 and AKT2 phosphorylation at S473." (PMID 32201539, 2020). "To investigate new therapeutic strategies for treatment-resistant breast cancer, we explored treatment targets using multigene panels, which showed high expression of HIF1A, RAF1, AKT2 and VEGFA in two TNBC cases." (PMID 31018595, 2019). "In contrast to the general findings in breast cancer, AKT1 knockdown in mouse embryo fibroblasts decreases migration and invasion, whereas AKT2 has an anti-migratory and anti-invasive effect." (PMID 31752925, 2019).
breast cancer (continued). "Combined with the data that PI3K-inhibitors can sensitize HER2-positive breast cancer cells to hypoxic stress and that overexpression of HER2 leads to overexpression of AKT2, a HER2-mediated pro-survival signaling via AKT2 is suggestable." (PMID 31752925, 2019). "In metastatic HER2-positive breast cancer a high AKT1 level was found in 12.2% of the samples and high AKT2 levels occurred in 35.1%." (PMID 31752925, 2019). "Poorly differentiated mammary tumors have low levels of AKT1 and AKT2, proposing a pivotal role of both isoforms in differentiation of breast tumors." (PMID 31752925, 2019). "Recently, in breast cancer, AKT1 has been shown to be involved in the local tumor growth while AKT2 in the distant tumor dissemination." (PMID 31781306, 2019). "In breast cancer, AKT1 had been demonstrated to suppress while AKT2 promotes migration and invasion." (PMID 31470874, 2019). "Altogether, our findings from experimental models and the TCGA meta-analysis support the idea that tumor progression in breast cancer differentially involves AKT1 and AKT2 isoforms." (PMID 28287129, 2017). "Therapy resistance is a major problem in metastatic breast cancer and markers of importance for endocrine resistance (Akt2, FOXO, mTOR, Myc, PI3KCA, and PTEN) were investigated in patients with HR+ breast cancer." (PMID 28489591, 2017). "The challenge now is to try new target therapies directed to AKT2-activated downstream signaling in combination with drugs that target PI3K and/or mTOR to achieve optimal efficacy in decreasing breast cancer progression." (PMID 28287129, 2017). "Our results also suggest WDR26 integrates interactions between Gβγ, PI3Kβ, and AKT2, which is critical for Gβγ-mediated PI3K/AKT signaling and function in breast cancer cells." (PMID 26895380, 2016). "The oncogenetic tree model was built on CNV of ErbB2, AKT2, KRAS, PIK3CA, PTEN, and CCND1 genes in 963 cases of tumors with sequencing and CNA data of human breast cancer from TCGA." (PMID 27190992, 2016). "In addition, CIP significantly downregulated the CXCL12 induced motility of breast cancer cells and molecular docking calculations revealed that all compounds bind to Akt2 kinase with high docking scores compared to the library of previously reported Akt2 inhibitors." (PMID 27097161, 2016). "In conclusion, combined analyses of AKT2, GNA12, GYS1 and SRF expression mimic the effects of miR-564 on tumor progression and survival of breast cancer patients." (PMID 27600857, 2016). "The repression of AKT2 and HK2 is consistent with a previous report on the ability of acidosis to repress AKT and glycolysis in breast cancer cells." (PMID 23613998, 2013). "The mutational and mRNA expression status of PIK3CA, PIK3R1 and AKT1, and expression status of other genes involved in the PI3K pathway (EGFR, PDK1, PTEN, AKT2, AKT3, GOLPH3, WEE1, P70S6K) were assessed in a series of 458 breast cancer samples." (PMID 24229379, 2013). "Since Ak1 and Akt2 were consistently expressed in the mammary tumors, MTB-IGFIR mice were crossed with Akt1−/− and Akt2−/− mice to determine the roles of Akt1 and Akt2 in mammary tumorigenesis." (PMID 23919516, 2013). "We found that patients with HER2-positive breast cancer treated with anti-HER2 targeted therapy with trastuzumab, whose tumours strongly expressed Akt2, had significantly longer overall survival from targeted treatment initiation (OSt)." (PMID 22842582, 2012). "In MDA-MB231 breast cancer cells treated with AKT isoform-specific siRNAs, prolonged suppression of the AKT2 isoform resulted G0/G1 cell cycle arrest through the downregulation of Cdk2 and cyclin D, and upregulation of p27." (PMID 22680924, 2012). "Introduction of Twist into breast cancer cells induces paclitaxel resistance and EMT, as well as AKT2 expression, which was amplified in breast cancer with acquired paclitaxel resistance." (PMID 21253528, 2011).
breast cancer (continued). "These analyses revealed that the interaction between Akt2 and EF1α depends on the phosphorylation status of Akt2, the most abundant and active isoform in HCC1937 cells and in breast cancer tumors." (PMID 19646290, 2009). "Unlike Akt1, Akt2 does not induce paladin phosphorylation and fails to inhibit breast cancer cell migration, instead it promotes breast cancer cell migration." (PMID 36180910, 2022). "In contrast, the expression of AKT2 somewhat overlapped with that of AKT1, suggesting that resulting phenotypes in mammary epithelial cells and, perhaps, in breast cancer, could be differentially affected by AKTs." (PMID 35892586, 2022). "Palladin, an actin-associated protein, was identified as a specific substrate for Akt1 and not Akt2 and was shown to inhibit Akt1-mediated cell migration in breast cancer cells." (PMID 34298660, 2021). "UCH-L1 (ubiquitin C-terminal hydrolase), a deubiquitinase, was shown to specifically interact with and activate Akt2 in MCF-7 breast cancer cells to promote invasion but did not affect cell proliferation." (PMID 34298660, 2021). "In vitro, downregulation of AKT2, but not AKT1 or AKT3, attenuated cell proliferation and 3D spheroid growth in PTEN-deficient prostate and breast cancer cells." (PMID 33276499, 2020). "Increased AKT2 levels in blood samples of metastatic or non-metastatic breast cancer patients serves as a marker for EMT and therefore predicts detection of CTCs." (PMID 31752925, 2019). "In contrast to our result, Akt1 but not Akt2 was found to modulate the expression of Cyclin D1 in lung and breast cancer cells." (PMID 31252679, 2019). "The isoform-specific effects can differ in the distinct stages of the breast cancer disease, e.g. AKT1 could promote tumor initiation and growth of the primary tumor, whereas AKT2 preferably promotes tumor progression and metastasis." (PMID 31752925, 2019). "Moreover, anchorage-independent growth and invasion were significantly reduced also in breast cancer cell lines with clear mesenchymal phenotype; with high expression of ALDH1A1, (MDA-MB-468 and SKBR3) after AKT2 silencing." (PMID 31357505, 2019). "In contrast to Akt1, which accelerates the induction of mammary tumours in transgenic mice, Akt2 can promote metastasis of tumour cells without affecting the latency of tumour development in certain systems." (PMID 29890731, 2018). "Certainly, in our breast cancer model, impairment of Akt1 or Akt2 does not produce identical biochemical profiles, as indicated by the effect on important proteins, such as Survivin or β-catenin." (PMID 29518912, 2018). "The higher AKT2 levels in ovarian cancer compared with breast cancer did not result in higher AKT2 phosphorylation." (PMID 30012111, 2018). "In contrast to Akt1, which accelerates the induction of mammary tumours in transgenic mice, Akt2 can promote the metastasis of tumour cells without affecting the latency of tumour development in certain systems." (PMID 29518912, 2018). "We conclude that AKT isoforms play specific roles in different steps of breast cancer progression, with AKT1 involved in the local tumor growth and AKT2 involved in the distant tumor dissemination, having AKT2 a poorer prognostic value and consequently being a worthwhile target for therapy." (PMID 28287129, 2017). "Transgenic overexpression of constitutively active AKT1 and AKT2 in oncogene-driven mouse models of breast cancer have revealed their opposing effects on cell migration and tumour metastasis, whereby AKT1 inhibits but AKT2 promotes the establishment of metastatic lesions." (PMID 28082369, 2017). "The results of MAPK antibody array showed that SAHA and TRAIL DR5 could affect the activity of AKT1, AKT2, and TOR protein in breast cancer cells." (PMID 29018571, 2017). "Given that the WDR26 fragments, WDR123-661 and WDR295-661, could still interact with AKT2 and PI3Kβ, we reasoned that they might also interfere with the function of the full-length WDR26 in breast cancer cells." (PMID 26895380, 2016).